ARHGEF28 (Rho guanine nucleotide exchange factor 28)
Description:
Functions as a RHOA-specific guanine nucleotide exchange factor regulating signaling pathways downstream of integrins and growth factor receptors. Functions in axonal branching, synapse formation and dendritic morphogenesis. Also functions in focal adhesion formation, cell motility and B-lymphocytes activation. May regulate NEFL expression and aggregation and play a role in apoptosis (By similarity).
Synonyms: p190RhoGEF; RGNEF; RIP2
Tractability: Small molecule: a structure with a bound ligand is known. Antibody: UniProt places it where antibodies can reach, with medium confidence; its Gene Ontology location is reachable by antibodies, with medium confidence; the Human Protein Atlas places it where antibodies can reach. PROTAC: ubiquitination databases record sites on it; its protein half-life has been measured.
Gene: Protein-coding gene on chromosome 5 (73,625,757 to 73,942,391, forward strand). Ensembl gene ENSG00000214944.
Subcellular location: Cytoplasm; Cell membrane
Subcellular location (Human Protein Atlas): Cytosol; Microtubules; Plasma membrane
Pathways (Reactome):
Signal Transduction: RHOA GTPase cycle; RHOB GTPase cycle; RHOC GTPase cycle
Developmental Biology: EPHB-mediated forward signaling
Gene Ontology:
Molecular function: guanyl-nucleotide exchange factor activity
Biological process: ephrin receptor signaling pathway; regulation of Rho protein signal transduction; regulation of small GTPase mediated signal transduction; small GTPase-mediated signal transduction
Cellular component: cytosol; cytoplasm; plasma membrane
Genetic constraint (gnomAD): Loss-of-function variants: 133 observed, 171.62 expected, observed/expected ratio (o/e) 0.77, 90% interval 0.67 to 0.89. The upper end of that interval is the gene's LOEUF score, 0.89, which puts it in group 3 of 6, group 1 being the genes least tolerant of losing a copy. Missense variants: 1,885 observed, 1,877.6 expected, observed/expected ratio (o/e) 1, 90% interval 0.97 to 1.04. Synonymous variants: 713 observed, 705.09 expected, observed/expected ratio (o/e) 1.01, 90% interval 0.95 to 1.08.
Gene-disease validity (ClinGen):
ClinGen rates the evidence that ARHGEF28 causes each of these diseases.
amyotrophic lateral sclerosis (semidominant): Limited. Amyotrophic lateral sclerosis (ALS) is a neurodegenerative disease characterized by progressive muscular paralysis reflecting degeneration of motor neurons in the primary motor cortex, corticospinal tracts, brainstem and spinal cord.
Homologues: Orthologues: chimpanzee ARHGEF28 (99% identical), macaque ARHGEF28 (96% identical), pig ARHGEF28 (83% identical), mouse Arhgef28 (81% identical), dog ARHGEF28 (80% identical), rat Arhgef28 (79% identical), guinea pig ARHGEF28 (78% identical), rabbit ARHGEF28 (77% identical), tropical clawed frog arhgef28 (51% identical), zebrafish arhgef28a (39% identical), Drosophila melanogaster cyst (16% identical), Caenorhabditis elegans prhg-1 (7% identical). Paralogues in human: ARHGEF18 (26% identical), ARHGEF2 (19% identical), ARHGEF12 (16% identical), ARHGEF11 (14% identical), ARHGEF1 (10% identical), PLEKHG6 (7% identical), NET1 (7% identical), ARHGEF3 (6% identical).
Diseases named in the same sentence as ARHGEF28 in open-access papers:
ARHGEF28 is named in the same sentence as 40 diseases in open-access papers, as found by Europe PMC text mining. Sharing a sentence is not in itself a finding about the gene and the disease. The quoted sentences say what the papers report.
amyotrophic lateral sclerosis (3 papers, 2014 to 2026). "The Rho guanine nucleotide exchange factor (RGNEF) protein encoded by the ARHGEF28 gene has been implicated in the neurodegenerative disease amyotrophic lateral sclerosis (ALS)." (PMID 32764283, 2020).
colon carcinoma (3 papers, 2015 to 2022). "ARHGEF28 promotes colon carcinoma cell motility and tumor progression via interaction with focal adhesion kinase (FAK)." (PMID 36241648, 2022). "In patients with colon cancer, elevated ARHGEF28 mRNA expression was found in advanced-stage disease." (PMID 35054411, 2021). "Moreover, ARHGEF28 promotes the local invasion of orthotopic colon carcinomas in mice." (PMID 25860875, 2015).
hearing loss (3 papers, 2020 to 2024). "The genes ARHGEF28, SYNJ2, and ACAN have been previously implicated in common variant studies of hearing loss (GWAS)." (PMID 38943082, 2024).
rectal cancer (2 papers, 2021 to 2024). A primary or metastatic malignant neoplasm that affects the rectum. "Meanwhile, the ARHGEF28 gene, associated with Rho guanyl-nucleotide exchange factor activity, has been previously reported to correlate with resistance to concurrent chemoradiotherapy in rectal cancer." (PMID 39034401, 2024). "Using Gene Ontology enrichment analysis, we discovered that ARHGEF28 overexpression might be linked to Wnt/β-catenin signaling in rectal cancer progression." (PMID 35054411, 2021). "The results showed that ARHGEF28 was the most significantly upregulated gene involved in CCRT resistance in rectal cancer." (PMID 35054411, 2021). "Altogether, these findings suggest that ARHGEF28 may promote rectal cancer progression through neurodegeneration-related genes and the Wnt/β-catenin signaling pathway." (PMID 35054411, 2021). "We conducted a gene co-expression analysis to speculate ARHGEF28 function in rectal cancer." (PMID 35054411, 2021). "Furthermore, the clinical relevance of ARHGEF28 in rectal cancer is not well understood." (PMID 35054411, 2021). "Accordingly, the correlations among the expression of ARHGEF28, the PS1 and Wnt/β-catenin pathways, and rectal cancer development and CCRT resistance require further investigation." (PMID 35054411, 2021). "Second, we did not investigate ARHGEF28 mRNA level in rectal cancer, which may further support our findings." (PMID 35054411, 2021).
chronic myeloid leukemia (1 paper, 2018). "ArhGEF28 interacts with RHOA which was found to be overexpressed in several cancers such as prostate cancer, gastric cancer and chronic myeloid leukemia." (PMID 30001383, 2018).
colorectal adenocarcinoma (1 paper, 2021). The most common type of colorectal carcinoma. "Applying the colorectal adenocarcinoma dataset from TCGA (n = 594), we appraised the top 200 differentially expressed genes that showed positive or negative correlations with ARHGEF28." (PMID 35054411, 2021).
colorectal carcinoma (1 paper, 2018). A malignant epithelial neoplasm that arises from the colon or rectum and invades through the muscularis mucosa into the submucosa. "Elevated ArhGEF28 expression promotes colorectal carcinoma invasion and tumor progression via interaction with focal adhesion kinase." (PMID 30001383, 2018).
kidney cancer (1 paper, 2024). Primary or metastatic malignant neoplasm involving the kidney. "Interestingly, CpGs in two genes encoding guannine nucleotide exchanging factors for Rho GTPase (ARHGEF28 and ARHGEF7) were hypomethylated in kidney cancer." (PMID 38336771, 2024).
motor neuron disease (1 paper, 2023). "Previous reports demonstrated the role of ARHGEF28 in modulating neuronal function or maintenance, and the formation of ARHGEF28 aggregates is involved in the pathogenesis of motor neuron disease." (PMID 37046301, 2023).
ovarian carcinoma (1 paper, 2022). A malignant neoplasm originating from the surface ovarian epithelium. "ARHGEF28 mRNA levels have also been found to be elevated in late-stage ovarian cancer and associated with decreased progression free and overall survival." (PMID 35931958, 2022).
psoriasis (1 paper, 2024). An autoimmune condition characterized by red, well-delineated plaques with silvery scales that are usually on the extensor surfaces and scalp. "Taking the intersection of these two algorithms, we finally obtained four specific gene biomarkers for psoriasis diagnosis (UGGT1\MMP9\CCNE1\ARHGEF28)." (PMID 38803495, 2024). "RT-qPCR results showed that compared to normal human epidermis, the expression of UGGT1, CCNE1, and MMP9 was significantly increased in patients with psoriasis, while ARHGEF28 expression was significantly decreased." (PMID 38803495, 2024). "Further we analyzed the expression of the four diagnostic genes screened by the two machine algorithms in 10 major immune cells and found that CCNE1 was elevated in CD4+ T cells as well as neutrophils in psoriasis lesions, and ARHGEF28 was elevated in mast cells." (PMID 38803495, 2024).
serous ovarian cancer (1 paper, 2021). "Elevated ARHGEF28 mRNA levels have been associated with late-stage serous ovarian cancer and worse clinical outcomes." (PMID 35054411, 2021).
synucleinopathies (1 paper, 2024). "Beyond known PD genes GBA1 and LRRK2, rare variants AD genes (CD33, CR1 and PSEN2) and Aβ toxicity modifiers involved in RhoA/actin cytoskeleton regulation (ARGHEF1, ARHGEF28, MICAL3, PASK, PKN2, PSEN2) were shared risk factors across synucleinopathies." (PMID 38496508, 2024).
tumor (10 papers, 2013 to 2025). "Genes such as ARHGEF28 and PPL were mutated in three of six ACC samples classified as other tumor sites." (PMID 30301885, 2018). "Interestingly, RAD51 and ARHGEF28 have previously been identified as a tumour suppressor and an oncogene respectively." (PMID 35931958, 2022).
cancer (5 papers, 2018 to 2026). A tumor composed of atypical neoplastic, often pleomorphic cells that invade other tissues. "Rgnef, (aka ARHGEF28 and p190RhoGEF), impacts cancer progression by regulating RhoA activity, an essential feature of focal adhesion dynamics and cell motility." (PMID 39493347, 2024).
ARHGEF28 also shares sentences with these, for which no sentence is quoted: leukemia (3 papers); schizophrenia (3); neurodegenerative disease (2); neurodevelopmental disorder (2); acute myeloid leukemia (1); atherosclerosis (1); autism (1); autism spectrum disorder (1); benign tumors (1); bipolar disorder (1); breast carcinoma (1); chronic kidney disease (1); cognitive decline (1); frontotemporal dementia (1); gastric cancer (1); hepatocellular carcinoma (1); Intellectual disability (1); melanoma (1); migraine (1); nasopharyngeal carcinoma (1); orofacial cleft (1); ovarian tumor (1); prostate carcinoma (1); sarcoma (1); Sepsis (1).